IL10 (interleukin 10)
Diseases named in the same sentence as IL10 in open-access papers (continued):
Sharing a sentence is not in itself a finding about the gene and the disease.
tumor (continued). "HPV-infected tumor cells release immune inhibitory factors such as transforming growth factor-β and interleukin-10 (IL-10), suppressing the activity and function of surrounding immune cells." (PMID 37876923, 2023). "According to literature data, IL-6 and IL-10 cytokines play a major role in the effects brought by macrophage activities in the tumor microenvironment." (PMID 37835437, 2023). "Positive correlations were found between FJX1 expression and tumor-associated macrophages (TAMs) and with immune-related genes such as TGFB1 and IL-10 and immunosuppressive pathway-related genes such as TGFB1 and WNT1." (PMID 37324001, 2023). "Th2 cells secrete IL-4 and IL-10 to mediate humoral immune responses, which leads to immune suppression and promotes tumor growth and metastasis." (PMID 38343446, 2023). "Furthermore, to better understand the association between antidepressant effects on tumor pathology and immune system activity, the T-cell proliferative response to concanavalin A (Con A), and the production of anti- and pro-tumoral cytokines: IL-1β, IL-10, and IFN-γ were also studied." (PMID 37409130, 2023). "MDSCs also interact with tumor macrophages and dendritic cells to influence their activity and upregulate the activity of Tregs through their production of IL-10, TGFβ, IFNγ, and CD40–CD40L interactions." (PMID 37376141, 2023). "For instance, antibodies against IL-10 have been shown to increase the presence of tumor-infiltrating lymphocytes (TILs) and promote tumor cell death in vitro." (PMID 37894457, 2023). "The activity of mast cells against tumours is regulated by interleukin-6, −8 and −10 (IL-6, IL-8 and IL-10) and chemokine ligands 3 and 5 (CCL3 and CCL5)." (PMID 37928785, 2023). "Activated ICOSHi CD4+ T cells expressed INFɣ instead of IL-10, which resulted in lysis of Mam-A expressing tumor cells." (PMID 36982282, 2023). "The other is the M2-like macrophage, induced by interleukin-13 and interleukin-4, expressing transforming growth factor β (TGF-β) and interleukin-10, which plays a role in promoting tumor growth." (PMID 38077373, 2023). "RNASE2 has been shown to regulate the production of cytokines (e.g., Interleukin-4 (IL-4) and Interleukin-10 (IL-10)), which can modulate the immune response and promote an immunosuppressive microenvironment, allowing tumor cells to escape immune surveillance." (PMID 37999824, 2023). "IL-10 is an anti-inflammatory cytokine that plays a crucial role in tumor killing and inhibits the production of IFNg, IL-2, IL-3, and TNFα." (PMID 37445686, 2023). "Interleukin (IL)-10-producing B (B10) cells are generated in response to signals from the tumor microenvironment and promote tumor growth by interacting with B10 cells." (PMID 37946227, 2023). "Moreover, TME rich in regulatory T-cells or tumor-associated macrophages (TAMs) reprogrammed by the tumor itself inhibit lymphocyte functions through macrophage polarization and the release of inhibitory cytokines such as interleukin (IL)-10, prostaglandins, and reactive oxygen species (ROS)." (PMID 36809986, 2023). "Breg cells can dampen effective anti-tumor responses by several mechanisms, including immunosuppressive cytokines (IL-10, IL-35 and TGF-b), activation of immune checkpoint pathways, and secretion of ineffective antibodies." (PMID 36765578, 2023). "Because IL-4 is implicated in secreting IL-10 and TGFB in the microenvironment due to the activation of STAT6, the M2a phenotype jumps to the tumor-promoting macrophage phenotype M2aM2cM2d hybrid." (PMID 37283734, 2023). "Interleukin-10 (IL-10) is known to suppress the anti-tumor T cell response and promote tumor growth." (PMID 37637038, 2023). "M2-type TAMs are induced by IL-4 and IL-13, leading to the release of immunosuppressive cytokines such as arginase 1, transforming growth factor-β, and IL-10, which promote tumour development while suppressing the immune response." (PMID 37426674, 2023).
tumor (continued). "These cells have lost their normal functions after being recruited and co-opted by the tumor through exposure to cytokines produced by the tumor cells, such as IL-4, IL-10, transforming-growth factor-β1 (TGF-β1), and prostaglandin E2 (PGE2)." (PMID 37082492, 2023). "There is also evidence that M-CSF secreted from tumor cells upregulates PPARβ/δ expression in myeloid cells to promote IL-10 expression and induce the polarization of M2-like macrophages." (PMID 37740232, 2023). "Collectively, MAPK can lead to ICI resistance through many discovered pathways: through decreasing T lymphocyte activity via IL-6 and IL-10; by increasing expression of PD-L1 on tumor cells; and by promoting the co-expression of several ICs in T lymphocytes." (PMID 37345111, 2023). "Hypoxia promotes tumor production of interleukin (IL-10) to recruit regulatory T cells (Tregs) to the TME, thereby blocking the antitumor immune response." (PMID 37719881, 2023). "The M2d sub-type, commonly referred to as tumor-associated macrophages (TAMs), promotes tumor progression by secreting TNFα, IL6, IL-10, TGFβ, and Vascular Endothelial Growth Factor A (VEGFA)." (PMID 37371552, 2023). "STAT3, as a member of the STATs family, has a highly complex regulatory bioactivity and can exert pro-tumor, pro-inflammatory or anti-inflammatory and tissue repair effects through the activation of ligands such as IL-6/IL-10." (PMID 37081874, 2023). "APCs contribute to IL-1, IL-6, IL-8, and IL-10 signaling along with macrophages and DCs in innate immunity and tumor cells in senescence." (PMID 37894479, 2023). "At tumor sites, MDSCs release IL-10 and free radicals such as peroxynitrite, and they also express indolamine 2,3 dioxygenase (IDO1) and arginase-1 (ARG1)." (PMID 37189689, 2023). "To date, there is emerging evidence also illustrating the roles of some ILs, including IL-6 and IL-10, in inhibiting antitumor immune responses and promoting tumor progression after incomplete ILTs." (PMID 36831664, 2023). "IL-10, one of the main anti-inflammatory cytokines produced by M2 macrophages, plays a significant part in regulating immune response and tumor progression." (PMID 37640741, 2023). "Th2 cells were known to suppress the development of Th1 cells and the release of IFN-γ, but they also secreted IL-4 and IL-10, which stimulated the growth of tumor cells." (PMID 37274225, 2023). "M2 macrophages are associated with the elevated expression of factors that promote angiogenesis and stimulate tumor cell proliferation in vivo, including matrix metalloproteinases, IL-10, and vascular endothelial growth factor." (PMID 37874419, 2023). "Tumor cells produce and secrete various immunomodulatory substances, including interleukin (IL)-10, IL-1β, galectin-1, and transforming growth factor-β, which regulate the behavior of infiltrating immune cells and establish a pro-tumoral microenvironment." (PMID 37533851, 2023). "High IL-10 levels correlate with amplified arginase activity, decreasing L-arginine levels but increasing L-Arg metabolite levels, which is crucial to tumor growth." (PMID 37508372, 2023). "The ensuing release of trophic factors, metabolic regulators, and immunosuppressive molecules by M2-like macrophages, including vascular endothelial growth factor A (VEGFA), PGE2, IL-6, IL-10, among others, ultimately accelerates tumor progression." (PMID 37968714, 2023). "In contrast, tumor-derived soluble factors M-CSF, IL-6, IL-1β, IL-4, IL-10, CCL2 initiate the immunosuppressive pathways that commit immature myeloid cells to become MDSCs and further promote the differentiation towards M-MDSC." (PMID 38304256, 2023). "The Th2-mediated immune response has been considered protumorigenic through anti-inflammatory cytokine secretion of IL-10 and promotion of pro-tumor B cell action." (PMID 37409975, 2023).
tumor (continued). "In the local tumor microenvironment, production of tryptophan metabolites, secretion of cytokines including IL-6 and IL-10, and an increase in membrane expression of checkpoint proteins like PD-L1 result in local immunosuppression." (PMID 38188300, 2023). "Macrophages M1 induced by interferon-gamma and LPS can kill tumour cells and pathogens, whereas macrophages M2 induced by IL-4, IL-10, and IL-13 exhibit anti-inflammatory activity and contribute to tumour invasion and angiogenesis." (PMID 37370746, 2023). "Similar observations were made when the anti-IL-10R antibody was used, which confirms that lowering the sensitivity of DCs to the influence of IL-10, significantly increases the effectiveness of created by DCs specific anti-tumor response." (PMID 37033926, 2023). "M2 macrophages have tumor-promoting properties, which can secrete anti-inflammatory factors such as IL-10, reduce the expression of pro-inflammatory factors, and inhibit adaptive immune response." (PMID 37124541, 2023). "Human interleukin-10 (IL-10) is known to be an immunosuppressive cytokine for anti-inflammation, however, IL-10 can enable the evasion of tumor cells through immunosuppression of the host immune system." (PMID 38102207, 2023). "Albeit later, Tc2 effector subpopulation was also demonstrated to be localized in the tumor site along with Th2 with higher IL-4 and IL-10 production which seemed to be correlated to tumor growth and metastasis in untreated mice." (PMID 37835465, 2023). "Tumor-associated factors such as TGF-β, platelet-derived growth factors (PDGFs), and Interleukins (IL-3, IL-6, IL-10) induce the production of reactive oxygen species (ROS) by the MDSCs." (PMID 37842239, 2023). "For example, NSCLC tumor cells secrete IL-10, TGFβ, and chemokine CCL20, which promote the proliferation, maturation, and recruitment of regulatory T-cells (Tregs) that suppress CD8+ T-cell-mediated cytotoxic killing." (PMID 38002256, 2023). "As an antitumor factor, IL-10 has been suggested to directly induce the expansion of tumor-specific CD8+ T cells in the tumor and cytotoxic activity of these cells." (PMID 38102207, 2023). "They primarily suppress immune cell activation and promote tumor cell growth and invasion by secreting anti-inflammatory cytokines, such as interleukin-10 (IL-10) and transforming growth factor-beta (TGF-β)." (PMID 38037023, 2023). "Tumor cells polarize TAMs to anti-inflammatory cells (M2), which produce IL-10 and TGF ß and express PD-L1, which in turn interact with NKs and T cells via the PD-1 and PD-L1 checkpoints." (PMID 37111629, 2023). "IL-10 is an immunosuppressor cytokine that inhibits the antigen-presenting process and unviable T-cells to recognize and eliminate tumor cells." (PMID 36903405, 2023). "Bregs have been detected in the peripheral blood of gastric cancer patients and mediate tumour cell escape through IL-10 signalling." (PMID 36890557, 2023). "We found that TGF-β and IL-10 were significantly downregulated in the tumor microenvironment with the NK cells treatment." (PMID 37253929, 2023). "The opposite effects of IL-10 probably depend on its interactions with other cytokines or with various factors in the tumor microenvironment." (PMID 37373957, 2023). "A high number of IL-10 and/or IL-35-producing Bregs are observed in the tumor stroma of PDAC murine models (KPC and KC) in addition to PDAC patient samples." (PMID 37033931, 2023). "This cytokine is considered a master switch from tumor-promoting inflammation to antitumor immunity, thus dysregulation in IL-10 levels can importantly contribute to carcinogenesis and tumor progression." (PMID 37359549, 2023). "M2 macrophages, marked by CD206, typically express high levels of anti-inflammatory cytokines (e.g., IL-10), growth factors and protease to support their pro-tumor functions." (PMID 37957722, 2023).
tumor (continued). "PGE2directly induces IL-10 release from macrophages, decreases IL-6 and TNF-α release, controls tumor-associated inflammation, and decreases the body’s anti-tumor immune response." (PMID 37153586, 2023). "An immunoregulatory cytokine IL-10 plays pleiotropic role in attributing both anti-tumor immunity and maintaining immune-suppressive condition." (PMID 38304256, 2023). "IL-10 suppresses inflammatory Th17 T cells and macrophages, which can trigger or promote tumor formation." (PMID 36874011, 2023). "MTE treatment decreased IL-10 levels in Jurkat cell supernatants both in single- and co-cultures, suggesting that MTE reduced the immunosuppressive effects of IL-10 on the tumor microenvironment." (PMID 37649480, 2023). "They stated that CENDE stimulated TAMs to produce IL-10 and Arginase-1, which then induced M2 polarization of TAMs to mediate the pro-tumor effect of CENDE." (PMID 36776333, 2023). "Secretion of IL-6 and IL-10 by SW620 and HCT116F3 cells were both undetectable, indicating the observed increase of IL-6 and IL-10 secretion in macrophage-tumour interaction came predominately from the macrophages." (PMID 37612278, 2023). "Much of the work looking at the tumour microenvironment has focused on lymphocytes where HTLV-1+ non-tumour cells assist in the growth of tumour cells particularly through IL-10 production." (PMID 37033972, 2023). "The strong antibody response in this patient, together with their cellular responses, reflected by high Th1 cytokine (IFNγ/IL-10, and TNFα/IL-10) ratios, correlated with the patient’s increase in progression-free survival and tumor reduction." (PMID 38203458, 2023). "IL10 has been shown to upregulate the production of cytotoxic enzymes and IFNγ in tumor infiltrating CD8 + T lymphocytes, thereby inducing antigen-presentation." (PMID 37259163, 2023). "Immunosuppressive molecules produced by tumor cells, such as IL-10, TGF-β, IDO or PD-L1, can directly suppress the immune response." (PMID 36969211, 2023). "For example, IL-12 partial agonists facilitated tumor clearance in vivo with reduced NK cell-mediated toxicities, and IL-10 partial agonists displayed myeloid cell-biased immunosuppression without T cell-mediated inflammation." (PMID 37339051, 2023). "What’s more, increased expression of miR-184-3p and decreased expression of Cd206 in tumor tissues in the miR-184-3p OE & hnRNPA2B1 KD group were confirmed by qRT-PCR, and the secretion of IL-10 detected by ELISA was also significantly reduced." (PMID 37957722, 2023). "The patients described illustrate the potential of serum IL-6, IL-8 and IL-10 for tumour monitoring in ALK + NSCLC." (PMID 37120670, 2023). "Compared to the 2 mg/kg protein treatment group, 8 mg/kg shTRAIL treatment not only significantly increased CD4+ T cells, Tregs, and M2 macrophages in the tumor but also upregulated IL-10 expression in intratumoral M2 macrophages." (PMID 37605148, 2023). "Cox regression analyses revealed significant associations (P < 0.005) of higher serum levels of IL-8, IL-10 and CAIX with worse OS in multivariable analyses, adjusted for established clinical prognostic factors including circulating tumor cells (CTCs)." (PMID 36945037, 2023). "M2 macrophages that differentiate in response to cytokines within the tumor microenvironment lose their anti-tumor efficacy and secrete immunosuppressive factors such as IL-10, TGF-β, and indoleamine 2,3-dioxygenase (IDO), thereby facilitating immune evasion." (PMID 37819576, 2023). "Potential confounding factors, such as tumor pathology, IMDC risk groups, ECOG performance status, and previous history of nephrectomy, were adjusted for serum IL-10 levels." (PMID 37151396, 2023). "The efficacy of pembrolizumab in reducing the tumor burden was amplified by 4.5-fold thanks to IL-10 suppression, paving the way for further investigations on the potential role of IL-10 as a predictive biomarker of resistance as well as a druggable target." (PMID 37373521, 2023).
tumor (continued). "Levels of TGF-β, which has anti-tumor effects in early-stage cancer but tumor–promoting effects in late-stage cancer, IL-10, and nitric oxide synthase 2 (NOS2) increase as tumors progress." (PMID 37108802, 2023). "It is believed that these two cell subtypes contribute to tumor progression, through the increase in IL-6, IL-10, and transforming growth factor β (TGF-β)." (PMID 36831674, 2023). "Among macrophages, M2 macrophages usually play an antiinflammatory role in the tumor microenvironment, with poor antigen presentation ability, low IL-12, and high IL-10, IL-4, and IL-13 secretion characteristics, as well as immunosuppressive effects." (PMID 38813495, 2023). "DEX treatment also decreased the levels of pro-inflammatory cytokines, including IL-1β, TNFα, IL-10, and IL-18, which are major tumor growth promoters." (PMID 37528154, 2023). "To investigate the underlying mechanisms of JMJD6-modulated macrophage activation, we analyzed the expression level of JMJD6 and M2-polarizing cytokines IL-10 in tumor-CM-activated macrophages." (PMID 37567973, 2023). "During the immune response against tumors, Tregs secrete cytokines including IL-35, TGF-β, and IL-10, which suppress anti-tumor immunity and facilitate the progression and formation of cancers." (PMID 37501987, 2023). "When a TIM-3 blockade was administered to Tregs that had infiltrated the tumor, it induced the production of IL10, a cytokine that is recognized to contribute to T cell exhaustion." (PMID 37376141, 2023). "We also examined the proportion of M2b macrophages in CT26 tumor tissues and found that treatment with 8 mg/kg smTRAIL significantly increased M2b macrophage infiltration (high IL-10 and low IL-12 levels)." (PMID 37605148, 2023). "On the other hand, CAFs alone or in concert with tumor cells differentiate monocytes into the protumor macrophage phenotype that exert an inhibitory effect on T cells by secreting IL-10, TGF-β, and arginase I." (PMID 37024932, 2023). "This condition is further exacerbated by immunosuppressive signals that are released from the primary tumour, particularly IL-10 and TGF-β." (PMID 37189436, 2023). "Breg cells promote tumor growth by inducing the formation of immunosuppressive TME by secreting IL-10 and IL-35 in response to the activation of STING signaling." (PMID 37264024, 2023). "Other TME-associated cells, such as T-regulated cells, dendritic cells, and tumor-associated adipose cells, also secrete pro-angiogenic factors, such as VEGFA, MMP9, IL10, TGF-β, and leptin, and consequently promote cancer angiogenesis." (PMID 36647777, 2023). "In the tumor region, the recruited monocyte is easily differentiated into M2-type TAMs due to the abundance of Th2 cytokines (IL-4, IL-10, IL-13), limiting antigen presentation and promoting immunosuppression." (PMID 38258072, 2023). "Overall, the downregulation of S100A9 plays a vital role in the process of IL-10 deficiency-mediated MPE suppression by the regulation of M1/M2 polarization, influencing tumor migration capacity, and apoptosis." (PMID 37533789, 2023). "The proinflammatory factors tumor necrosis factor (TNF-α), IL-6, IL-10, IL-23, nitric oxide (NO) and reactive oxygen species (ROS) secreted by M1 macrophages can significantly increase the inhibition of tumor cell proliferation." (PMID 36969211, 2023). "Combined treatment with IL-10 and PD-1 blockers enhances the expansion and function of tumor-infiltrating CD8+ T cells, resulting in a synergistic anti-tumor effect in metastatic melanoma and ovarian cancer." (PMID 37359549, 2023). "In patients with upregulated Tim-3 expression, a higher frequency of IL-10-producing tumor-infiltrating B cells is widespread." (PMID 37567938, 2023). "To determine the redundancy of serum cytokine abundance for tumour monitoring, we checked the correlations of IL-6, IL-8 and IL-10 with these two ctDNA parameters." (PMID 37120670, 2023).